HIF1A (hypoxia inducible factor 1 subunit alpha)
Diseases named in the same sentence as HIF1A in open-access papers (continued):
Sharing a sentence is not in itself a finding about the gene and the disease.
cancer (continued). "The oxidation of phosphatase and tensin homolog (PTEN) results in AKT-mediated cell survival and proliferation, while the oxidation of prolyl hydroxylases leads to hypoxia-inducible factor 1α (HIF-1α) stabilisation, resulting in a profound metabolic rewiring of cancer cells." (PMID 31819197, 2020). "TGase 2 is also induced under hypoxic stress in cancer cells by HIF-1α activation." (PMID 32260198, 2020). "Because the shift toward utilising aerobic glycolysis in proinflammatory macrophages is governed by HIF-1α stabilisation, this finding in cancer may appear incongruous to our findings that SAHA promoted the shift to glycolysis." (PMID 32793237, 2020). "In addition to the basic interaction between miRNAs and the 3’-UTR of HIF-1α, miRNA-mediated transcriptional regulation of HIF-1α expression is a common mechanism in cancer progression." (PMID 32014012, 2020). "The aberrant activation of AC020978/PKM2/HIF-1α glycolysis cascade might be cancer's comprehensive metabolic adaptation to allow cell survival under glucose starvation and hypoxia cellular stress." (PMID 32308748, 2020). "Moreover, clustering of detached cancer cells creates a hypoxic environment and triggers a hypoxia-inducible factor 1-alpha (Hif1α)-mediated metabolic switch that restricts reactive oxygen species accumulation." (PMID 32616784, 2020). "However, others have shown that the loss of a single HIF-α isoform (either HIF-1α or HIF-2α) is compensated by the enhanced expression of the other and promote survival during cancer development." (PMID 33383924, 2020). "Since hypoxia is a common feature of many solid tumors, we explored whether the HIF-1α/SNHG11 axis functions in other cancers." (PMID 33060856, 2020). "Interestingly, K32 resides near two residues found to be mutated in various human cancers, S28Y and R30Q, which alter the SET7/9 consensus site when mutated to prevent methylation, thus leading to increased HIF-1α stability." (PMID 33383924, 2020). "Additionally, septins have been increasingly linked to cancer oncogene expression, including EGFR, HER2 and the HIF-1α/angiogenesis axis." (PMID 32094384, 2020). "HIF-1α serves as major bioenergetics sensor in cancer cells in solid and hematologic malignancies." (PMID 32354000, 2020). "Thus, HIF-1α is sufficient to activate important signal transduction pathways that promote cancer progression." (PMID 32846951, 2020). "The proposed pathway of HIF-1α modulation may have physiological relevance not only in cancer but also in other pathological conditions as well as normal biological processes characterized by low oxygen levels." (PMID 31912870, 2020). "Furthermore, HIF-1α-mediated proangiogenic signaling is not limited to cancer cells, and can occur in other cell types within the TME, including cancer-associated fibroblasts (CAFs)." (PMID 32316260, 2020). "Considerable work has been done to characterize the role of HIF-1α in cancer metastasis 7-10." (PMID 32724467, 2020). "Hypoxic inducible factor, HIF-1α is a well-known modulator of glycolysis in cancer cells." (PMID 33193345, 2020). "Reprogramming of glucose metabolism in cancer cells is driven by HIF-1α and c-Myc." (PMID 32585857, 2020). "Furthermore, ABZ can inhibit glycolysis in cancer cells via phosphoenol pyruvate carboxykinase inhibition and can determine the inhibition of hypoxia inducible factor (HIF-1α)." (PMID 33158183, 2020). "In addition, increased ROS production stabilizes HIF-1α, enhancing cancer-related fibroblasts through glycolysis, leading to the Warburg effect and the secretion of lactate to feed nearby cancer cells, ultimately inducing RR352." (PMID 32355263, 2020). "The connection between lincRNA-p21 and HIF-1α in hypoxia was recently confirmed in liver cancer cells including xenograft models as well as in a study investigating the influence of lincRNA-p21 on radio sensitivity of hypoxic cancer cells." (PMID 32640630, 2020).
cancer (continued). "Additionally, the antitumor activity of chlorogenic acid is mediated through the induction of cancer cell differentiation, and vanillic acid inhibits hypoxia-induced HIF-1α expression in various human cancer cell lines." (PMID 33426081, 2020). "As HIF-1A is firmly associated with the radioresistance of cancer cells, we think that LCN2 might interact with HIF-1A to facilitate the development of a radioresistant phenotype in NPC." (PMID 33604288, 2020). "Previous studies have revealed that HIF1A was overexpressed in multiple types of human cancer." (PMID 32210827, 2020). "Stimulation of glucose utilization and fatty-acid oxidation by adiponectin occurs through activation of AMPK which is an insulin-independent pathway that regulates energy metabolism, though Hypoxia-inducible factor-1α (HIF-1α) regulates glycolysis in cancer cells by inactivation of AMPK." (PMID 32082261, 2020). "The drugs that indirectly affect the HIF1a pathway and HIF1a inhibitors might be a good alternative in the adjuvant therapy of certain cancers." (PMID 32872192, 2020). "Numerous studies aiming at the multifarious genes targeted by HIF-1α-induced miR-210 overexpression have highlighted the broad involvement of this mechanism in intricate cancer pathologies, including proliferation, apoptosis, angiogenesis, autophagy, metastasis, and radioresistance." (PMID 32014012, 2020). "Positive regulation of HIF-1α on miRNAs is common in cancer progression." (PMID 32014012, 2020). "Previous studies suggested that moderate hypoxic conditions might trigger an EMT process via HIF-1α, leading different human cancer cells to significantly increase their invasiveness." (PMID 33297475, 2020). "Moreover, it can be considered a good metabolic modifier in acidosis that downregulates HIF-1α transcriptional program and glycolytic enzymes, forcing cancer cells to rely mainly on OXPHOS to meet their demand of ATP." (PMID 33291643, 2020). "Decreased HIF1α expression can reduce the viability of SKOV3 cancer cells." (PMID 32986358, 2020). "Thus, the feedforward loop of the regulation of the expression and activity HIF1α and ROS initiates a redox adaptation response, thereby increasing the tolerance of cancer cells to oxidative stress, with upregulation of survival pathways." (PMID 32354000, 2020). "TMEM207 abolishes the binding of WWOX with HIF-1α to enhance cancer growth." (PMID 32764489, 2020). "Moreover, disruption of AMPK signaling, either though inhibition of AMPK itself or its upstream kinase LKB1, induces elevated HIF-1α protein expression and a pro-growth metabolic reprogramming in cancer cells." (PMID 32531951, 2020). "In the view of previous research findings, it is clear that HIF-1α takes important roles in hypoxia-induced EMT through promoting wide range of EMT transcription factors through multiple signaling pathways in various cancer types." (PMID 32322559, 2020). "It has been found that exosomes are more likely to be produced and secreted in the hypoxic cancer microenvironment, because excessive hypoxia-inducible factor-1α (HIF-1α) regulates the activation of small GTPase Rab27a (a major regulator of exosomal synthesis)." (PMID 32746850, 2020). "A rapidly growing body of evidence indicates that HIF-1α enhances cancer development." (PMID 33376737, 2020). "Additionally, XO increases HIF-1α expression and activates NF-κB pathway, which promotes inflammation and cancer progression." (PMID 32575703, 2020). "Finally, the adaptive response to hypoxia in cancer cells contributes, through the overexpression of HIF-1α, to the activation of glucose transport and thus to glycolysis and the pentose phosphate pathway." (PMID 33008042, 2020). "HIF-1α may upregulate PDK1, which promotes PGC-1α activity to reduce cancer cell damage caused by ROS accumulation." (PMID 33266219, 2020).
cancer (continued). "Besides lipid synthesis, HIF1-α was also reported to increase the lipid levels of cancer cells through the direct upregulation of Fatty Acid Binding Protein 3 (FABP3) and FABP7, both involved in lipid uptake." (PMID 32932943, 2020). "Finally, we demonstrated the involvement of RSKs and HIF-1α in the regulation of PpIX accumulation in human cancer cell lines." (PMID 33335181, 2020). "Importantly, increased ALS2 expression correlates with augmented HIF-1α levels in cancer biopsies, making it a promising marker for the detection of HIF-1α and hypoxia-related cancers." (PMID 33339852, 2020). "Furthermore, propofol has been shown to reduce of HIF-1a levels in cancer cells in vitro, with potential inhibitory effects on angiogenesis and, therefore, on tumour growth." (PMID 32863874, 2020). "Chemo- or radiotherapy induced redox stress could cause upregulation of HIF-1α which drives the activity of both MCT4- and MCT1- cancer cells." (PMID 33028364, 2020). "Additionally, the overexpression of HIF-1α was proven to be connected with a poor prognosis in several cancers in a study." (PMID 33256814, 2020). "Meanwhile, although some meta-analyses have been performed to investigate the association between HIF-1α SNPs and cancer risk, most of these did not incorporate all previously published research." (PMID 33154192, 2020). "Finally, we evaluate the potential of prospective HRN biomarkers for the diagnosis and prognosis of cancer, as well as the potential clinical application of regulatory mechanisms shared between HIF-1α and ncRNAs in cancer treatment." (PMID 32014012, 2020). "This protection is associated with an induced expression of the angiogenesis-regulating factor HIF-1a, a mechanism that may be protective in the setting of reperfusion injury, but which promotes malignant recurrence in cancer surgery." (PMID 32863874, 2020). "Given the bulk of hypoxic regions in solid tumors, elucidating links between PAK and HIF-1α in hypoxic cancer cells may further unveil details in mechanisms of cancer development." (PMID 31931758, 2020). "Immunohistochemical analyses of several types of cancer show an overexpression of HIF-1α." (PMID 33135539, 2020). "Downregulation of SDHD results in an increased stabilization of HIF1α and cancer cell survival." (PMID 32486505, 2020). "We observed that CAV1 presence in cancer cells was associated with diminished HIF1α activity rather than protein levels and linked this to reduced nitrosylation in the presence of CAV1." (PMID 32825247, 2020). "Notably, HIF1α can activate the Wnt pathway, stimulating the self-renewal of BCSCs through a direct activation of cancer stemness capability, but also inhibiting PPARγ activity." (PMID 33352766, 2020). "Recent researches in cancer biology at the cellular and molecular levels claimed that the HIF-1α pathway is a main survival pathway for which novel strategies of cancer therapy could be developed." (PMID 32597160, 2020). "However, this was inconsistent with the previous reports, in which Ablating HDAC4 signaling induced Hif1α protein acetylation, reduced Hif1α protein level in cancer cell lines, and inhibited endothelial tumor angiogenesis." (PMID 32354322, 2020). "AC020978/PKM2/HIF-1α positive feedback loop triggers a cascade reaction in aerobic glycolytic and cancer progression, which may be a promising metabolism blocker target for antitumor therapy." (PMID 32308748, 2020). "Furthermore, correlation of over-expression and co-localization of both HK II and HIF-1α in cancer cells near necrosis regions have been reported." (PMID 32252351, 2020). "Finally, the fungal product Chaetocin has been shown to de-regulate HIF-1α pre-mRNA splicing and inhibit hepatoma and ovarian cancer growth in cancer models by reducing angiogenesis." (PMID 32536347, 2020). "Expression of HER2 and HIF1A has been shown to correlate within other cancer subtypes." (PMID 31952211, 2020).
cancer (continued). "Numerous drugs inhibiting the activity of HIF-1α had been identified as anti-cancer agents." (PMID 32312328, 2020). "Another HIF-1α-suppressing lncRNA was identified by Xiang and coworkers, who found that c-Myc mediated suppression of lncRNA isocitrate dehydrogenase 1 antisense RNA 1 (IDH1-AS1) in cancer cell lines activates HIF-1α-induced glycolysis under normoxic conditions." (PMID 32640630, 2020). "Since ERK/HIF-1α/VEGF signaling reportedly regulates tumorigenesis in several cancers, we hypothesized HIF-1α might be suppressed by CRM197." (PMID 32695675, 2020). "It has been reported that HSP70 binds and stabilizes HIF-1α in cancer cell lines." (PMID 32121660, 2020). "Furthermore, the PI3K/Akt pathway is also known for consequently regulating HIF-1α, a transcription factor involved in regulating many target genes in which the protein products are recognized for their significant roles in cancer-related processes." (PMID 33097763, 2020). "Similarly, an epigenetic-based gene silencing and hypoxia inducible factor-1α (HIF-1α)-dependent mechanism were also found to play important roles in the regulation of ct-OATP1B3 expression in cancer tissues." (PMID 32534581, 2020). "Thus, the regulation of HIF-1α nuclear transfer by ncRNAs is a promising regulatory mechanism to block the oncogenic function of HIF-1α in cancer progression." (PMID 32014012, 2020). "HIF-1α might therefore be a useful biomarker for feline cancer therapy and prediction of the clinical outcome, and thus developing compounds that inhibit HIF-1α may be a potential approach to FMGCs treatment." (PMID 32375802, 2020). "In this report, we demonstrated that inorganic arsenic (iAs) induces generation of the cancer stem-like cells (CSCs) through Nrf2-dependent HIF1α activation, and the subsequent metabolic reprogramming from mitochondrial oxidative phosphorylation to glycolysis in epithelial cells." (PMID 32226544, 2020). "HIF1α is a transcription factor that has been shown to induce TET1 transcription in cancer cells." (PMID 31935962, 2020). "Furthermore, they suggest that the hypoxia/Hif1α-dependent regulation of the metabolism in cancer is modulated through a Fbp2-dependent sensing of the energy and redox state of a cell." (PMID 31947613, 2020). "This study indicated that the effect on HIF-1α might make tetrahydrocurcumin a potential candidate for preventing cancer metastasis." (PMID 32486019, 2020). "In addition, HIF-1α also contributes to the metabolic adaptation of cancer cells by upregulating vascular endothelial growth factor (VEGF) and GLUT1 during hypoxia." (PMID 32927797, 2020). "Some HIFs, such as HIF1A, ARNT, EPAS1, and HIF3A, were linked with unfavorable outcomes for pan-cancer, while two HIFs including ARNTL and ARNT2 were associated with favorable outcomes in pan-cancer." (PMID 33299416, 2020). "Furthermore, MEK activates the transcription of HIF-1α and induces resistance to cancer therapeutics under hypoxic conditions." (PMID 33335181, 2020). "For example, WWOX regulates the function of HIF-1α in promoting cancer progression." (PMID 32764489, 2020). "As HIF-1α promotes glycolysis and provides cancer cells with lactate and glutamate, increased reactive oxygen species (ROS) production in cancer cells induces the uptake of intermediate metabolites of the tricarboxylic acid (TCA) cycle in mitochondria indirectly." (PMID 32787888, 2020). "The knockdown of SOD2-dependent ROS generation up-regulates HIF-1α expression in carcinoma cells." (PMID 33202982, 2020).
cancer (continued). "Several studies have revealed that PKC-δ is activated by hypoxia and subsequently increases the HIF-1α stability in human cancer cells, and PKC-α seems to be involved in the activation of HIF-1α along with cAMP response element binding protein (CREB) in rat tissue." (PMID 30813635, 2019). "Conversely, MIF protects HIF-1α from proteasomal degradation in cancer cells." (PMID 30634708, 2019). "TGF-β has also been reported to induce metabolic reprogramming of stromal cells, such as cancer-associated fibroblasts (CAFs), where CAFs overexpressing TGF-β ligands show increased autophagy and HIF-1α activation and concomitantly reduced oxidative phosphorylation." (PMID 30736412, 2019). "Cross-talk between the hypoxia/HIF-1α and Rho pathways has already been investigated in different cell models, such as cancer cells, fibroblasts, endothelial cells, and MSCs; however, the effects of hypoxia on RhoA levels and activation show many differences among cell types." (PMID 30925808, 2019). "However, the translational mechanism of HIF-1α is still poorly understood in cancer progression, even though the translational component contributes to approximately 40–50% of HIF-1α total proteins under hypoxia." (PMID 31291975, 2019). "In addition to its role in phosphoenolpyruvate phosphorylation, PKM2 acts as a cofactor for HIF1α, a transcription factor critical for the Warburg effect and the transcription of glycolytic enzymes in cancer cells." (PMID 31044177, 2019). "Hypoxia inducible factor-1 (HIF-1α) is known to induce lymphangiogenesis in several cancers." (PMID 31921870, 2019). "HIF-1α has been recognized as an important drug target in kinds of cancers." (PMID 31291975, 2019). "Findings showing that ApoA-I can affect the expression levels of transcription factors, such as HIF-1α, suggest that ApoA-I may have profound effects on metabolic pathways in cancer cells." (PMID 31374929, 2019). "The fact that expression of the hypoxia markers HIF-1α and CA-IX were significantly lower in the hysterectomy specimens compared with the endometrial biopsies suggests that the cancer stem cell markers studied were more stable at the protein level and resistant to delays in fixation." (PMID 31214492, 2019). "Consequently, overexpression of OPN promoted development of cells with cancer stem-like characteristics, including chemoresistance, by modulating integrin αvβ3-NF-κB-hypoxia-inducible factor-1 alpha (HIF-1α) signaling axis." (PMID 31349670, 2019). "The rs2057482 polymorphism in the hypoxia inducible factor 1 subunit alpha (HIF1A) gene has been reported to be associated with a risk of several types of cancer, but this association has not yet been definitively confirmed." (PMID 31744467, 2019). "Hypoxia, a common phenomenon in malignant tumors, promotes cell proliferation regulated by HIF-1α." (PMID 31077234, 2019). "In immune cells, including T lymphocytes and myeloid cells, cellular activation of HIF-1α has also been reported to occur in an oxygen-independent manner during inflammation triggered by infection and cancer, and to involve transcriptional in addition to post-translational mechanisms." (PMID 31681292, 2019). "Indeed, reduced oxygen concentrations are known to potentiate the glycolytic phenotype of cancer cells in a HIF1A-dependent manner." (PMID 31159361, 2019). "Additionally, HIF-1α elevation has been shown to benefit cancer cells by promoting anabolic metabolism, including the pentose phosphate pathway (PPP), which can provide hypoxic cancer cells with nucleotides as building blocks." (PMID 31078780, 2019). "In contrast, HIF-1α can be stabilized under both normoxia and hypoxia in cancer cells." (PMID 31600993, 2019). "This PH inactivation blocks HIF-1α degradation in cancer cells." (PMID 31600993, 2019). "Finally, HIF-1α contributes to the aerobic glycolysis in cancer cells by upregulating several key glycolytic enzymes, thereby increasing the uptake of key nutrients including glucose." (PMID 30708988, 2019).